DEFB118 (defensin beta 118)
Description:
Host defense peptide that exhibits antimicrobial activity against both Gram-negative bacteria, such as E.coli and S.typhimurium, and Gram-positive bacteria, such as S.aureus and B.subtilis. Inhibits cell adhesion of E.coli on intestinal epithelial enterocytes. Causes rapid permeabilization of both the outer and inner membrane of E.coli, leading to morphological alterations on the bacterial surface. Binds to bacterial lipopolysaccharides (LPS) with high affinity, and may thereby be involved in immunoregulation through LPS neutralization. May contribute to epididymal innate immunity and protect the sperm against attack by microorganisms.
Synonyms: DEFB-18; ESP13.6; C20orf63; ESC42; dJ1018D12.3
Tractability: Antibody: UniProt places it where antibodies can reach, with high confidence; UniProt predicts a signal peptide or a membrane-spanning region; its Gene Ontology location is reachable by antibodies, with medium confidence.
Gene: Protein-coding gene on chromosome 20 (31,368,601 to 31,373,923, forward strand). Ensembl gene ENSG00000131068.
Subcellular location: Secreted
Pathways (Reactome):
Immune System: Beta defensins; Defensins
Gene Ontology:
Molecular function: lipopolysaccharide binding; membrane destabilizing activity; protein binding
Biological process: antimicrobial humoral immune response mediated by antimicrobial peptide; defense response to Gram-negative bacterium; defense response to Gram-positive bacterium; innate immune response; killing of cells of another organism; negative regulation of cell adhesion; negative regulation of lipopolysaccharide-mediated signaling pathway; cell-matrix adhesion; defense response to bacterium; spermatogenesis
Cellular component: extracellular region
Genetic constraint (gnomAD): Loss-of-function variants: 3 observed, 2.93 expected, observed/expected ratio (o/e) 1.02, 90% interval 0.44 to 1.86. That is too few expected variants to judge how well the gene tolerates losing a copy. Missense variants: 159 observed, 152.53 expected, observed/expected ratio (o/e) 1.04, 90% interval 0.92 to 1.19. Synonymous variants: 63 observed, 56.82 expected, observed/expected ratio (o/e) 1.11, 90% interval 0.9 to 1.37.
Homologues: Orthologues: chimpanzee DEFB118 (96% identical), macaque DEFB118 (89% identical), dog DEFB118 (38% identical), rat Defb21 (30% identical), mouse Defb21 (28% identical). Paralogues in human: DEFB121 (25% identical), DEFB132 (25% identical), DEFB128 (23% identical), DEFB123 (22% identical), DEFB125 (22% identical), DEFB127 (20% identical), DEFB115 (20% identical), DEFB116 (17% identical), DEFB124 (17% identical), DEFB108C (16% identical), DEFB119 (16% identical), DEFB129 (16% identical), and 7 more.
Diseases named in the same sentence as DEFB118 in open-access papers:
DEFB118 is named in the same sentence as 2 diseases in open-access papers, as found by Europe PMC text mining. Sharing a sentence is not in itself a finding about the gene and the disease. The quoted sentences say what the papers report.
Candida infection (1 paper, 2022). "Furthermore, these and previous findings indicate that oral fibroblasts can recognize β-glucan in oral epithelia during Candida infection, which promotes the induction of DEFB118 as an antifungal response." (PMID 35507985, 2022).
cancer (1 paper, 2020). A tumor composed of atypical neoplastic, often pleomorphic cells that invade other tissues. "Interestingly, 5 out of the top 10 hub genes in the network are cancer genes, including ELF3, SLC10A4, ANXA9, DEFB118, KRT8." (PMID 32064261, 2020).